CLIC5 (CLIC family member 5)
Description:
In the soluble state, catalyzes glutaredoxin-like thiol disulfide exchange reactions with reduced glutathione as electron donor (By similarity). Can insert into membranes and form non-selective ion channels almost equally permeable to Na(+), K(+) and Cl(-). Required for normal hearing. It is necessary for the formation of stereocilia in the inner ear and normal development of the organ of Corti (By similarity). May play a role in the regulation of transepithelial ion absorption and secretion. Is required for the development and/or maintenance of the proper glomerular endothelial cell and podocyte architecture. Plays a role in formation of the lens suture in the eye, which is important for normal optical properties of the lens (By similarity).
Synonyms: DFNB102; DFNB103; MST130; MSTP130
Tractability: Antibody: UniProt places it where antibodies can reach, with high confidence; UniProt predicts a signal peptide or a membrane-spanning region; its Gene Ontology location is reachable by antibodies, with medium confidence; the Human Protein Atlas places it where antibodies can reach. PROTAC: ubiquitination databases record sites on it.
Gene: Protein-coding gene on chromosome 6 (45,880,827 to 46,080,348, reverse strand). Ensembl gene ENSG00000112782.
Subcellular location: Cytoplasm, cytoskeleton (Isoform 1); Cytoplasm, cell cortex; Membrane; Apical cell membrane; Cytoplasm; Mitochondrion; Cell projection, stereocilium; Golgi apparatus (Isoform 2); Cytoplasm, cytoskeleton, microtubule organizing center, centrosome
Subcellular location (Human Protein Atlas): Plasma membrane; Nuclear speckles
Pathways (Reactome):
Sensory Perception: Sensory processing of sound by inner hair cells of the cochlea; Sensory processing of sound by outer hair cells of the cochlea
Gene Ontology:
Molecular function: protein binding
Biological process: chloride transport; sensory perception of sound; female pregnancy
Cellular component: actin cytoskeleton; apical plasma membrane; extracellular exosome; Golgi apparatus; membrane; plasma membrane; cytoplasm; mitochondrion; cell cortex; centrosome; cytoskeleton; stereocilium
Genetic constraint (gnomAD): Loss-of-function variants: 18 observed, 21.66 expected, observed/expected ratio (o/e) 0.83, 90% interval 0.57 to 1.23. The upper end of that interval is the gene's LOEUF score, 1.23, which puts it in group 5 of 6, group 1 being the genes least tolerant of losing a copy. Missense variants: 340 observed, 323.52 expected, observed/expected ratio (o/e) 1.05, 90% interval 0.96 to 1.15. Synonymous variants: 159 observed, 137.8 expected, observed/expected ratio (o/e) 1.15, 90% interval 1.01 to 1.32.
Homologues: Orthologues: chimpanzee CLIC5 (96% identical), macaque CLIC5 (96% identical), rabbit CLIC5 (95% identical), guinea pig CLIC5 (94% identical), rat Clic5 (93% identical), mouse Clic5 (93% identical), dog CLIC5 (92% identical), pig CLIC5 (92% identical), tropical clawed frog clic5 (84% identical), zebrafish clic5a (76% identical), zebrafish clic5b (76% identical), Caenorhabditis elegans exl-1 (28% identical), and 30 more. Paralogues in human: CLIC4 (74% identical), CLIC6 (72% identical), CLIC2 (62% identical), CLIC1 (61% identical), CLIC3 (48% identical), EEF1G (20% identical), GSTT2 (20% identical), GSTT2B (20% identical), GDAP1L1 (18% identical), GSTZ1 (18% identical), GDAP1 (17% identical), GSTO1 (16% identical), and 2 more.